GPRC5A (G protein-coupled receptor class C group 5 member A)
Diseases named in the same sentence as GPRC5A in open-access papers (continued):
Sharing a sentence is not in itself a finding about the gene and the disease.
tumor (81 papers, 2009 to 2025). "Because Gprc5a deficiency enhances the transformed phenotype of lung epithelial cells, NF-κB–mediated GPRC5A repression contributes to neoplasia of lung epithelial cells." (PMID 36413416, 2023). "Similar responses were observed for the putative tumour suppressor GPRC5A; loss of either protein resulted in an increased expression, thereby contributing to cellular differentiation and suppression of colony formation." (PMID 32128997, 2020). "In our research, we found the existence of AT2 cells in Gprc5a-deficient mice in the tumor region of the lungs." (PMID 32157214, 2020). "HNSCC is associated with suppressed expression of GPRC5A, which is positively associated with tumor grade, along with the activation of STAT3." (PMID 30417009, 2018). "We found that repression of GPRC5A occurred at an early stage of tumorigenesis, and associated with tumor progression." (PMID 28270740, 2017). "The relative prevalence of these malignant states was then translated into an eight−gene expression signature derived from the GPRC5A+ program that stratifies patients into high− and low−risk groups with distinct tumor microenvironments and predicted drug sensitivities." (PMID 41567189, 2025). "GPRC5A was also found to be associated with the tumor immune microenvironment." (PMID 39006081, 2024). "As seen in Gprc5a−/− mice, KACs were closely associated with tumour cells in pseudotime." (PMID 38418883, 2024). "Moreover, existing evidence suggests GPRC5A is up-regulated in tumors and further associated with tumor metastasis." (PMID 35255904, 2022). "Interestingly, in tissues with high GPRC5A expression (lung), malignant cells are associated with reduced expression, indicating a tumor-suppressive role of the membrane protein." (PMID 32719397, 2020). "Repressed GPRC5A associates with increased tumor grade and activated STAT3, which may be used as a prognostic marker for tumor progression of HNSCC." (PMID 28270740, 2017). "The results show that the lungs of Gprc5a−/− mice were not only susceptible to silica-induced inflammation, but also experienced tissue damage, fibrogenic response, and increased hyperplasia or neoplasia." (PMID 26447616, 2015). "Besides, in vivo experiments revealed that only coculture with Lgr5 cells or the supernatant from Lgr5 cells that both isolated from Gprc5a-deficient mice could lead to tumor formation." (PMID 32157214, 2020). "GPCRs are considered to be amongst the best drug targets for many diseases, and therefore, GPRC5A represents a new opportunity to exploit the notion of “conditional synthetic lethality”—leveraging the cancer‐associated nature of hypoxia to selectively target tumour cells for death." (PMID 30143543, 2018). "Thus, the causal relationship between silica exposure and neoplasia may be reproduced in Gprc5a−/− mouse model that is susceptible to both pulmonary inflammation and lung tumorigenesis." (PMID 26447616, 2015). "Similarly, the protein product encoded by GPRC5A, another retinoic acid responding gene whose expression is heavily downregulated by the feeder layer, was also reported to function as a potential tumor suppressor gene." (PMID 23443166, 2013). "Collectively, these data demonstrate that GPRC5A is a direct target of miR-31-5p and mediates its anti-tumor effects." (PMID 41306963, 2025). "Consistent with this, analysis of in vivo mouse models (subcutaneous/intraperitoneal) showed that exosome treatment reduced GPRC5A expression, inhibiting tumor growth and metastasis." (PMID 41306963, 2025). "Second, tLyP-1-modified exosomes exhibited enhanced tumor-targeting specificity and exerted anti-tumor effects via the miR-31-5p-GPRC5A axis." (PMID 41306963, 2025).
tumor (continued). "GPRC5A also exhibits a tumour-suppressive effect in breast cancer cells by inhibiting EGFR (epidermal growth factor receptor)." (PMID 40427604, 2025). "The correlation between GPRC5A expression and tumor immune microenvironment was analyzed using the GEPIA2 database." (PMID 39006081, 2024). "Another scRNA‐seq result showed that 21 vital tumour mutant genes were identified in bladder cancer samples, with mutations in ARID1A, GPRC5A and MLL2 increasing the self‐renewal capacity of tumour cells and contributing to tumorigenesis." (PMID 38520221, 2024). "To investigate the effect of GPRC5A on tumor growth, we next established a subcutaneous xenograft tumor model." (PMID 36735162, 2023). "We propose that NF-κB–mediated GPRC5A repression contributes to dedifferentiation or neoplasia in lung epithelial cells." (PMID 36413416, 2023). "We showed that NF-κB, via interaction with retinoic acid receptor (RAR), inhibits RAR-mediated transcription of GPRC5A, switching the gene expression from homeostasis to dedifferentiation in lung epithelial cells for neoplasia." (PMID 36413416, 2023). "SAHA treatment significantly suppressed tumor growth and restored GPRC5A expression compared with the placebo group." (PMID 36413416, 2023). "In comparison to NC group, tumor growth in miR-135b-5p antagomir+Ad-NC group was markedly slower, but the speed of tumor growth was significantly restored after overexpressing GPRC5A." (PMID 35027543, 2022). "The analysis of clinical characteristics indicated that patients with high-expression of GPRC5A had larger tumor size, higher TNM stages, higher tumor grade, and more positive resection margin." (PMID 33753999, 2021). "In particular, GPRC5A is involved in the activation of proteins and signaling pathways often related to tumor development, such as NF-κB, STAT, and FAK/Src." (PMID 34522225, 2021). "Patients with high expression of GPRC5A showed larger tumor size, higher TNM stages, higher tumor grade, and more positive resection margin." (PMID 33753999, 2021). "Patients with high expression of GPRC5A showed larger tumor size, higher Tumor Node Metastasis (TNM) stages, higher tumor grade, and more positive resection margin." (PMID 33753999, 2021). "Significant differences were observed between the high-expression and low-expression of GPRC5A patients regarding size of tumor (T), TNM stage, grade (G) and resection status (all P < 0.05)." (PMID 33753999, 2021). "Further, multivariate cox regression analysis showed that tumor Grade, GPRC5A expression and IMUP gene expression were independent prognostic indicators in PAAD development." (PMID 34819098, 2021). "In one immunohistochemical study, staining of 367 CRC tumor samples displayed GPRC5A localization to the luminal membrane of 193 (62%) samples." (PMID 34290978, 2021). "Other studies have reported that GPRC5A is an orphan G-protein coupled receptor with an intriguing dual behavior, acting as an oncogene in certain cancer types and as a tumor suppressor in other cancer types." (PMID 33680947, 2020). "Deletion of this gene confers susceptibility to endotoxin-induced pulmonary edema and injury, indicating that GPRC5A is critical for lung homeostasis and functions as a tumor suppressor." (PMID 33187367, 2020). "To validate the clinical relevance of our findings, we next assessed RSK, EphA2, and GPRC5A by immunofluorescence in human HGSC tumor tissue sections." (PMID 32115889, 2020). "To extend the analysis further, we also analyzed GPRC5A mRNA levels in human tumor samples in TCGA using the GEPIA database." (PMID 32060421, 2020). "Studies with GPRC5A knockout mice suggested a tumor-suppressive function of the protein in lung adenocarcinoma." (PMID 32719397, 2020). "Knockdown of hsa_circ_006100 in vivo inhibited tumour growth by upregulating expression of the tumour suppressor miR‐195; this led to reduced GPRC5A levels and a downregulation the EMT phenotype." (PMID 31318114, 2019).
tumor (continued). "Recently, an orphan G protein-coupled receptor GPRC5A has been identified as a hypoxia-induced protein, which protects hypoxic tumor cells from apoptosis via the HIF-GPRC5A-RhoA-YAP axis." (PMID 31072060, 2019). "Further, the known tumor suppressors DCC and GPRC5A were underexpressed with underlying reduced copy number." (PMID 31682594, 2019). "Future studies profiling Gprc5a−/−Kras mutant CSCs vs. parental cell xenotransplants may further aid in elucidating expression programs that embody an augmented malignant phenotype by CSCs, including expression cues associated with the host immune response and tumor microenvironment." (PMID 31001473, 2019). "Using immunohistochemical methods, we showed that GPRC5A expression was significantly higher in subcutaneous tumor xenografts of the 8348SOCS3 group compared with the 8348plv group." (PMID 29662621, 2018). "Our work identifies GPRC5A as a previously unrecognised mediator of tumour cell survival specifically during hypoxia." (PMID 30143543, 2018). "Increased GPRC5A expression is significantly related to aggressive clinical parameters (larger tumor size, diffuse type, serosal invasion, and lymph node metastasis) and shorter overall survival (OS)." (PMID 30417009, 2018). "Lastly, KRT19 and GPRC5A can act as tumor suppressors in other cancers, but have pro-oncogenic functions in PDAC." (PMID 29675033, 2018). "KEGG pathway and gene ontology analyses revealed that GPRC5A mRNA expression strongly correlated with genes related to Hippo signalling, particularly in later stage tumours." (PMID 30143543, 2018). "As in the PDAC cells, GPRC5A was the highest expressed GPCR in the tumor samples (∼fourfold more highly expressed than any other GPCR)." (PMID 29872392, 2018). "Lower GPRC5A mRNA levels have been reported in seven cell lines established from patients-derived tumor xenografts." (PMID 30417009, 2018). "Several parallel studies showed that GPRC5A exerts its tumor suppressive effect by regulating the NF-κB and EGFR/STAT3 signaling pathways." (PMID 30417009, 2018). "BxPc3 and PaCaDD 165, which have a low GPRC5A mRNA and protein level, show both a KRAS wild type indicating that RAI3 expression increases with malignancy of a tumor." (PMID 28114355, 2017). "Presumably, the epigenetic changes during tumor development and progression prevent the inhibitory effects of GPRC5A overexpression on Cp, LCN2 and POSTN in NSCLC cells." (PMID 28088789, 2017). "Our recent study showed that increased levels of TGFβ, fibrogenic response and EMT-like features as well as neoplasia were induced in the lungs of Gprc5a-ko mice compared to wild-type mice following exposure to silica nanoparticles." (PMID 28088789, 2017). "Taken together, these data indicate that repression of GPRC5A is correlated with tumor grade, and poor prognosis of HNSCC." (PMID 28270740, 2017). "This assumption is supported by the inverse correlation of GPRC5A expression and tumor grade of HNSCC." (PMID 28270740, 2017). "GPRC5A expression not only inhibited IR-induced normal cells oncogenic transformation, but also suppressed some oncogenic characteristics in tumour cells." (PMID 27273304, 2016). "GPRC5A is an orphan G-protein coupled receptor with an intriguing dual behavior, acting as an oncogene in some cancers and as a tumor suppressor in other cancers." (PMID 27415424, 2016). "In this study, we show that GPRC5A functions as a tumour suppressor to prevent IR-induced lung tumorigenesis, which involves GPRC5A at ER to suppress synthesis for a group of membrane-associated proteins and EGFR is the most important among them." (PMID 27273304, 2016). "The high levels of GPRC5A protein in PDAC tumor cells persisted even when the cells metastasized to other organs like liver." (PMID 27415424, 2016). "Taken together, the gene expression program for neoplasia in the lungs of Gprc5a−/− mice following silica exposure coincided with exacerbated tissue injury and increased fibrogenic response." (PMID 26447616, 2015).
tumor (continued). "Taken together, compared to those from wild-type mice, lungs from Gprc5a−/− mice exhibited an increased neoplasia that coincided with increased tissue damages and fibrogenic response following silica exposure." (PMID 26447616, 2015). "One possible explanation for these opposite observations is that the tumor-suppressive function of GPRC5A can be inactivated under certain conditions." (PMID 25311788, 2014). "As the levels of GPRC5A mRNA decrease from normal people to patients with either COPD or adenocarcinoma it is likely that in this context GPRC5A acts as a tumor suppressor." (PMID 25621293, 2014). "In vitro experiments revealed that overexpression of GPRC5A in OSCC CAL27 cells suppresses the cells' anchorage-independent growth activity, indicating that GPRC5A plays a tumor suppressor role in oral tissue." (PMID 25621293, 2014). "We also observed that a number of genes with tumor suppressor function (GPRC5A, ELF1, NAB2, Sema4D, ACPP, MAP2, RUNX1) persistently remained downregulated in response to radiation exposure." (PMID 23216862, 2012). "In future studies, it would be worthwhile to investigate the tumor incidence of Gprc5a knockout mice exposed to varying and increases doses of NNK." (PMID 20686609, 2010). "SOD3, and GPRC5A were identified as early marker genes expressed in evolving tumor stem cells." (PMID 41282138, 2025). "GPRC5A acts as an oncogene or tumor suppressor in different cancers." (PMID 39723668, 2025). "Together, the machine−learning importance ranking, tumor–normal contrasts across TCGA and GSE17558, and survival analyses converge on FAM189A2 as a protective hub within the risk framework, in line with its enrichment in the GPRC5A+ malignant subpopulation." (PMID 41567189, 2025). "GPRC5A has been extensively investigated in cancer cells for its role as a tumor suppressor." (PMID 36766718, 2023). "Taken together, it is tempting to suggest that GPRC5A might have a tumor-suppressive function in lung epithelial cells." (PMID 36781501, 2023). "It seemed that GPRC5A could affect signaling related to hypoxia, tumor environment, Rho GTPase, NF-kB and EGF response." (PMID 33753999, 2021). "GPRC5A expression may also be related to hypoxia, a key characteristic of many tumor microenvironments." (PMID 34290978, 2021). "Interestingly, GPRC5A expression inversely correlated with miR‐1205 and miR‐382 levels in tumor tissues." (PMID 33543830, 2021). "GPRC5A (G protein-coupled receptor class C group 5 member A) is a protein coding gene that demonstrates a dual behavior—acting as an oncogene in certain cancers and as a tumor suppressor in other cancers." (PMID 34572861, 2021). "Meanwhile, GPRC5A, which can behave as an oncogene or tumor suppressor depending on context, was upregulated in CTBs with coincident downregulation of STAT3, suggesting that it may function as a tumor suppressor in this system." (PMID 34121116, 2021). "Besides, the protein expression of GPRC5A in tumor was higher than in normal pancreas validated via IHC on the online tool The Human Protein Atlas." (PMID 33753999, 2021). "In PDAC, GPRC5A is involved in tumor proliferation, invasion and metastasis 28,29." (PMID 34522225, 2021). "GPRC5A confers resistance to tumor-promotive effects of silica." (PMID 32778128, 2020). "Additionally, the overexpression of GPRC5A suppressed tumor growth by inducing cell apoptosis in vivo." (PMID 33680947, 2020). "While tumor‐suppressive and oncogenic functions have been reported for this orphan receptor, possible GPRC5A functions in OC remain unknown." (PMID 32115889, 2020). "Moreover, the data of qRT-PCR and Western blot revealed that circ_0000144 and GPRC5A were dramatically down-regulated and miR-623 was strikingly up-regulated in tumor tissues derived from sh-circ_0000144-transducing cells." (PMID 32766708, 2020).
tumor (continued). "As increased MDM2 expression suppresses GPRC5A, a tumor suppressor gene in A549 cells, our data might suggest that phenanthriplatin treatment could reduce MDM2 and thereby nullify the effect of GPRC5A to suppress tumor progression." (PMID 33302475, 2020). "Notably, cisplatin increased EphA2 and pS897/pY588, and BI‐D1870 blocked both the constitutive and cisplatin‐induced EphA2‐pS897 in the HGSC cells with high GPRC5A, concurrently increasing tumor‐suppressive EphA2‐pY588." (PMID 32115889, 2020). "Of note, GPRC5A in primary tumors was inversely correlated with the reduction in tumor burden at the end of treatments, defined by the objective response rate (ORR), and with platinum sensitivity, considering sole administration or combination with taxane (P = 0.034 and 0.011)." (PMID 32115889, 2020). "Within a tumor type, a large majority of individual tumors express such overexpressed GPCRs at far higher levels than corresponding normal tissue (e.g., GPRC5A); a subset of GPCRs are expressed in >90% of PDAC tumors at abundances greater than in any normal pancreas sample." (PMID 31765370, 2019). "The highest expressed GPCRs in PDAC tumors (as an example, this finding is generalizable to other tumor types) are generally overexpressed compared to normal tissue and include orphan receptors (e.g., GPRC5A and ADGRF4/GPR115) and GPCRs with known agonists (e.g., GPR68)." (PMID 31765370, 2019). "Indeed, this tyrosine residue in GPRC5A has been shown to be phosphorylated by RTKs including EGFR to suppress its tumor suppressor function." (PMID 29946230, 2018). "Additionally, GPRC5A knockout enhances the transformed phenotype in normal and tumor cells through the aberrant activation of the EGFR/STAT3 signaling pathway." (PMID 30417009, 2018). "Gprc5a, a lung tumor suppressor gene, is preferentially expressed in lung tissue." (PMID 28088789, 2017). "Moreover, we found that repression of GPRC5A is associated with activated STAT3 in HNSCC, which correlates with tumor progression." (PMID 28270740, 2017). "Thus, repression of GPRC5A has been linked to upregulation of STAT3 signaling pathway in HNSCC, which contributes to tumor progression." (PMID 28270740, 2017). "In addition, we examined the subcellular localization of GPRC5A protein in both normal and tumor cells via immunofluorescence staining." (PMID 28270740, 2017). "Importantly, increased hyperplasia or neoplasia coincided with silica-induced tissue injury and fibrogenic response in lungs from Gprc5a−/− mice." (PMID 26447616, 2015). "In summary, Gprc5a deficiency exacerbated the pathologic processes induced by silica exposure, with increased lung injury, persistent pulmonary inflammation, induction of EMT-like characteristics and neoplasia." (PMID 26447616, 2015). "Thus, persistently up-regulated EGFR signaling for tissue repair appeared to be hijacked for neoplasia program in the lungs of Gprc5a−/− mice following silica exposure." (PMID 26447616, 2015). "Thus, silica-induced pulmonary inflammation and injury contribute to increased neoplasia development in lungs from Gprc5a−/− mouse model." (PMID 26447616, 2015). "Taken together, these observations strongly support out hypothesis, that EGFR-mediated tyrosine phosphorylation of GPRC5A inactivates some of the tumor suppressor activities of GPRC5A." (PMID 25311788, 2014). "However, in another study researchers reported that GPRC5A mRNA levels are lower in seven newly established cell lines from patient derived tumor xenografts." (PMID 25621293, 2014). "Moreover, G0S2 and GPRC5A have been reported to possess tumor suppressive or apoptosis-inducing effects." (PMID 23587162, 2013). "Herein, we investigated the effects of bacterial-induced COPD-like inflammation and tobacco carcinogen-enhanced tumorigenesis/inflammation in the retinoic acid inducible G protein coupled receptor knock out mouse model (Gprc5a-/- mouse) characterized by late-onset, low multiplicity tumor formation." (PMID 22239913, 2012).